DUX4 (double homeobox 4)
Diseases named in the same sentence as DUX4 in open-access papers (continued):
Sharing a sentence is not in itself a finding about the gene and the disease.
leukemia (22 papers, 2017 to 2025). A malignant (clonal) hematologic disorder, involving hematopoietic stem cells and characterized by the presence of primitive or atypical myeloid or lymphoid cells in the bone marrow and the blood. "More importantly, the breakdown in TCF12–IGH::DUX4 cooperation impaired IGH::DUX4‐driven leukaemia cell survival, caused sensitivity to the chemotherapy." (PMID 38115701, 2023). "Recent studies suggested that DUX4-rearranged leukemia was associated with 93% of 5-year EFS and OS in pediatric patients." (PMID 35269896, 2022). "Our results identified a subgroup of cases clustering with known leukemia subtypes, e.g., DUX4-positive, and subgroups characterized by mutations in PAX5 and IKZF1, resulting in more cases being assigned to a defined subgroup." (PMID 34830809, 2021). "Consistently, TAAT repeat was also frequently associated with leukemia cell lines that contain DUX4/IGH." (PMID 30315230, 2019). "We defined a novel relapse-associated gene expression signature for DUX4 leukemias." (PMID 30862934, 2019). "It is also notable that translocations of DUX4 into the IgH locus have been implicated in B cell leukemia, and that all leukemia-associated translocations lack the 3′ region of the DUX4 ORF, leading to overexpression of a version of DUX4 lacking the C-terminus." (PMID 30446688, 2018). "DUX4 translocation to the silenced allele may thus provide the selective advantage required to achieve the precise level of expression to promote fitness of leukemia cells." (PMID 31243274, 2019). "The expressions of CLEC12Aalt and CLEC12A were consistently increased in leukaemia cells that harbored both IGH::DUX4 and TCF12." (PMID 38115701, 2023). "In order to investigate the cofactors of IGH::DUX4, integrated mining of Chromatin immunoprecipitation (ChIP)‐sequencing and RNA‐sequencing of leukaemia cells and patient samples were conducted." (PMID 38115701, 2023). "The leukaemia cell line NALM‐6 can stably express IGH::DUX4 endogenously, and hence provide us with a perfect opportunity to monitor the effect of TCF12 depletion on IGH::DUX4 in leukaemia cells." (PMID 38115701, 2023). "Supportively, knockdown and knockout of TCF12 significantly reduced expression of IGH::DUX4‐driven target genes in leukaemia REH (a precursor B‐cell leukaemia cell line) and NALM‐6 cells (a precursor B‐cell leukaemia cell line)." (PMID 38115701, 2023). "Deregulation of ETS transcription factor gene ERG occurs in 5–10% of DUX4-rearranged leukemia cases." (PMID 35269896, 2022). "By contrast, activation of the wild-type IGH allele would lead to moderate expression of DUX4 from the silenced IGH-DUX4 allele, ensuring leukemia cell viability." (PMID 31243274, 2019). "In marked contrast, the loss/break-down of CTD has enabled DUX4/IGH to cause B-cell arrest and proliferation, and hence serves as an oncogenic driver in leukemia." (PMID 29572508, 2018). "Consistent with previous observations, human leukemia cell line Reh cells harboring the newly identified DUX4/IGHs showed the expression of ERGalt." (PMID 29572508, 2018). "ERG-related leukemia is a B cell precursor acute lymphoblastic leukemia (BCP ALL) subtype characterized by aberrant expression of DUX4 and ERG transcription factors, and highly recurrent ERG intragenic deletions." (PMID 28415578, 2017). "Moreover, CD371 expression was found to be notably higher in patients with IGH::DUX4 leukaemia than in other subtypes." (PMID 38115701, 2023). "Previous studies have reported that AGAP1 was highly expressed in IGH::DUX4 types of leukaemia." (PMID 38115701, 2023). "The dysregulated genes were identified in the two‐dimensional (2D) representation of the gene expression profile following t‐distributed stochastic neighbour embedding dimensionality reduction, wherein patients with DUX4‐fused leukaemia exhibited pronounced upregulation of TCF12." (PMID 38115701, 2023).
leukemia (continued). "Altogether, these results helped to define a previously unrecognised TCF12‐mediated positive self‐feedback regulatory mechanism in IGH::DUX4 leukaemia, which holds the potential to function as a pivotal drug target for the management of this particular form of leukaemia." (PMID 38115701, 2023). "Regarding the IGH::DUX4‐driven transactivation and alternative splicing, which are the main reasons behind this acute leukaemia outbreak, it remains unclear how transcriptional cofactors contribute to this oncogenic process." (PMID 38115701, 2023). "However, it is possible to identify this subtype with the use of only one single cell surface protein, because the CD371 antigen is pathognomonic of DUX4-positive leukemia." (PMID 35269896, 2022). "DUX4 (double homeobox 4) plays an essential role in patients’ leukemias carrying the recently described DUX4-IGH (immunoglobulin heavy chain) translocation, while the downstream mediator DDIT4L (DNA-damage-inducible transcript 4 like) is identified as therapeutic vulnerability." (PMID 34580292, 2021). "CXCR4 and chemotaxis genes in DUX4-translocated leukemia may contribute and enhance leukemia-stroma interactions facilitating DUX4 blasts to survive treatment." (PMID 30862934, 2019). "If an IGH-DUX4 rearranged allele were selected for activation—which is possible as not all B-ALLs express functional IGH24,25, the resulting highly expressed DUX4 would likely be too toxic to permit the survival of leukemia cells, leading to cell death." (PMID 31243274, 2019). "For Bosutinib as an indication for ALL, the similarity to other (lymphoblastic) leukemia types was revealed, along with significant disease genes AICDA and DUX4." (PMID 39372928, 2024). "The next closely related motifs came from TFs PU.1 (a crucial factor in both hematopoiesis and leukaemia) and Tcf12, bearing 21.23% and 29.78% similarities to IGH::DUX4, respectively." (PMID 38115701, 2023). "Supportively, when TCF12 expression was inhibited in these leukaemia cells, the IGH::DUX4‐driven transcription was significantly reduced." (PMID 38115701, 2023). "Based on these results observed in B‐ALL patients, leukaemia cells and structural simulation, an IGH::DUX4 cofactor TCF12 was proposed." (PMID 38115701, 2023). "To further evaluate the effects of DUX4 overexpression in fully transformed leukemia cells, we introduced DUX4 into Nalm6 cells which already harbor the IGH-DUX4 translocation, confirming GFP-tagged DUX4 protein expression by western blot." (PMID 31243274, 2019). "The results showed that fully transformed leukemia cells would not tolerate further overexpression of DUX4 with a significant increase in apoptosis when comparing DUX4 transduced cells with the empty vector control (p = 0.0124)." (PMID 31243274, 2019). "In this leukaemia subtype, TCF12 could act as a cofactor in regulating the transcriptional mechanism of IGH::DUX4 via a positive self‐feedback regulatory interplay between IGH::DUX4 and TCF12." (PMID 38115701, 2023). "It is typically necessary to prove the diagnosis of secondary tumors, rather than a lineage switch at relapse, for types of leukemia that demonstrate increased lineage plasticity, such as AL with KMT2A, ZNF384 or DUX4 gene rearrangements or early T-cell acute lymphoblastic leukemia (ETP-ALL)." (PMID 40565358, 2025).
muscular dystrophy (19 papers, 2011 to 2024). Muscular dystrophy (MD) refers to a group of more than 30 genetic diseases characterized by progressive weakness and degeneration of the skeletal muscles that control movement. "As previously demonstrated, DiPRO1 has the capacity to regulate DUX4 and BSR satellite DNA, implicated as pathological loci in the muscular dystrophy FSHD." (PMID 39009887, 2024). "For instance, recent work from Ferlini's lab studied chitosan‐shelled nanobubbles as a DDS for PMO ASO to suppress the expression of Double homeobox 4 (DUX4) in a facioscapulohumeral muscular dystrophy (FSHD) cell model." (PMID 35092179, 2022). "FSHD represents a unique case for a muscular dystrophy since the expression of DUX4, normally restricted at the embryonic development, is aberrantly reactivated at the wrong time and in the wrong place." (PMID 34943834, 2021). "A number of therapeutic approaches are being developed to antagonize the events preceding and following DUX4 expression that leads to muscular dystrophy." (PMID 33067535, 2020). "Moreover, it also results in enhanced silencing at the facioscapulohumeral muscular dystrophy associated macrosatellite-array, D4Z4, resulting in enhanced repression of DUX4 encoded by this repeat." (PMID 37749075, 2023). "We also know that developmental genes can be detrimental later in life; for example, double homeobox protein 4 (DUX4) plays a role in early embryonic development and is normally epigenetically silenced afterwards, yet its aberrant expression in muscle causes muscular dystrophy in patients." (PMID 36973715, 2023). "Double homeobox 4 (DUX4) transcription factor is a main player in development of facioscapulohumeral (FSHD) dystrophy, one of the most common muscular dystrophies." (PMID 29254187, 2017).
rhabdomyosarcoma (19 papers, 2009 to 2025). A rare aggressive malignant mesenchymal neoplasm arising from skeletal muscle. "The DUX4 promoter activated a linked luciferase reporter gene (DUX4-luc) in human rhabdomyosarcoma and C2C12 myoblasts, activity that was strongly reduced by mutations in either its TACAA box or a 5’ GC box binding Sp1." (PMID 40855454, 2025). "There was a 27% overlap of transcripts that are differentially expressed by DUX4 in mouse C2C12 myoblasts compared to human RD rhabdomyosarcoma cells expressing DUX4, despite effects associated with comparing mouse myoblasts with human cancer cells." (PMID 27744317, 2016). "The DUX4 promoter was active in human rhabdomyosarcoma cells and depended on the TACAA and a GC box." (PMID 40855454, 2025). "Double homeobox 4 (DUX4) is another prominent TF that activates HERV-L LTRs in rhabdomyosarcoma cells (muscle cancer cells)." (PMID 38540701, 2024). "Recently, strong DUX4 immunoexpression was identified as a hallmark of CDS, differentiating it from other round cell sarcomas (EWS, alveolar rhabdomyosarcoma, synovial sarcoma, and desmoplastic small round cell tumor)." (PMID 39441368, 2024). "In all 3 cell lines, immortalized myoblasts, rhabdomyosarcoma cells, and 293 T epithelial cells, we observed a DUX4 dose-responsive reduction in FAIM2 protein, shortly after induction." (PMID 35468884, 2022). "Previous studies have demonstrated that transduced expression of DUX4 in rhabdomyosarcoma cell lines led to apoptosis." (PMID 31243274, 2019). "Similar to its activity in immortalized human myoblasts, DUX4 was able to downregulate MYOD1 expression in the rhabdomyosarcoma cell lines." (PMID 30446688, 2018). "To identify genes and pathways necessary for DUX4-mediated apoptosis, we performed an siRNA screen in an RD rhabdomyosarcoma cell line with an inducible DUX4 transgene." (PMID 28273136, 2017). "Alterations in desmin abundance or PTMs in rhabdomyosarcoma TE671 cells that have decreased its interaction with DUX4/4c have most probably allowed us to detect other protein partners on these more accessible targets." (PMID 26816005, 2016). "Co-transfection of these constructs with pCS2-DUX4 or the empty pCS2 backbone in TE-671 rhabdomyosarcoma cells confirmed that the activation of FRG2 is mediated by DUX4 protein expression." (PMID 25789155, 2014). "Both proteins are expressed in human-derived rhabdomyosarcoma cell lines, and DUX4 is expressed in myoblasts of FSHD patients." (PMID 19473516, 2009). "To ensure that its activity was generally involved in cell death driven by DUX4, and not specific to a cell type, we tested inhibiting miR-3202 in an additional dox-inducible-DUX4 myogenic cell type, a rhabdomyosarcoma line, and in a non-myogenic cell type, 293 T cells." (PMID 35468884, 2022).
Ewing sarcoma (18 papers, 2014 to 2025). A small round cell tumor that lacks morphologic, immunohistochemical, and electron microscopic evidence of neuroectodermal differentiation. "DSRCT is a member of the small round cell sarcoma tumor type which includes other oncogenic fusion protein driven tumors such as Ewing sarcoma, CIC::DUX4, and BCOR::CCNB33." (PMID 38575753, 2024). "We identified a high frequency of fusions in Ewing’s sarcoma, where 86.2% of samples contained fusions (25 of 29 samples), including 21 samples (72.4%) harboring an EWSR1 fusion and 4 samples (13.8%) harboring a DUX4 fusion." (PMID 40711866, 2025). "While Ewing sarcoma harbors a fusion gene that is formed by the fusion of the EWSR1 gene to the ETS gene family, CDS is characterized by the occurrence of a fusion gene CIC-DUX4 that is formed by the fusion of CIC (Capicua) and DUX4 (Double homeobox 4 gene)." (PMID 34685592, 2021).
acute lymphoblastic leukemia (11 papers, 2017 to 2025). Leukemia with an acute onset, characterized by the presence of lymphoblasts in the bone marrow and the peripheral blood. "DUX4 rearrangements, including IGH::DUX4, are associated with a favorable prognosis in B-cell acute lymphoblastic leukemia (B-ALL)." (PMID 41228238, 2025). "With the continuous development of modern sequencing technology, several new oncogenic fusions, including DUX4 fusions in B‐cell progenitor acute lymphoblastic leukaemia (BCP‐ALL), have been identified." (PMID 38115701, 2023). "Moreover, a chromosomal translocation involving DUX4 homeodomains drives pathogenesis of acute lymphoblastic leukaemia." (PMID 36158201, 2022). "Finally, recurrent translocations giving rise to pro-oncogenic fusion proteins containing DUX4 portions have been described in round-cell sarcoma and acute lymphoblastic leukemia (ALL)." (PMID 34943834, 2021). "DUX4 activity was recently detected in acute lymphoblastic leukemia." (PMID 29254187, 2017). "Moreover, a RAG-dependent ERG deletion or alternative transcript, following DUX4-IGH rearrangement, has been shown to promote B-cell precursor acute lymphoblastic leukemia (ALL) with a favorable outcome." (PMID 37735473, 2023).
B-cell acute lymphoblastic leukemia (7 papers, 2019 to 2025). A neoplasm of lymphoblasts committed to the B-cell lineage, typically composed of small to medium-sized blast cells. "DUX4 is known to work as an oncogenic driver causing B cell acute lymphoblastic leukemia in adolescents and young adults, which suggests that DUX4 also works as an oncogenic driver in the organs of FSHD1 patients." (PMID 36336708, 2023). "In addition, high expression of DUX4 protein with an aberrant C terminus is frequently identified in B cell acute lymphoblastic leukemia." (PMID 36336708, 2023). "In B-cell acute lymphoblastic leukemia (B-ALL), DUX4 rearrangements (DUX4-r) define a distinct genomic subtype affecting 5–10% of cases, which is more frequent among older children and teenagers." (PMID 40940582, 2025).
viral infection (7 papers, 2016 to 2025). "Aberrant reactivation of DUX4 in somatic tissues has been associated with different diseases, including virus infection, various neoplasms, and, most importantly, FSHD." (PMID 39273067, 2024). "We first hypothesized that the induction of DUX4 might be part of an antiviral response of the cell to viral infection triggered by a herpesviral pathogen associated molecular pattern (PAMP), or by herpesviral induction of a cellular DNA-damage response (DDR)." (PMID 38168299, 2023). "Other pathological roles of DUX4, such as participation in cancer and viral infection, are also highlighted." (PMID 40855454, 2025). "We also found that DUX4 expression led to an accumulation of double stranded RNAs (dsRNAs) that induced a cell death pathway evolved to protect against viral infections." (PMID 28273136, 2017). "Knockdown of RNASEL, a gene involved in innate immunity to viral infection, rescued RD cells from DUX4 lethality (DUX4 Z-Score = 3.71) and had minimal effect on the doxycyline induction of the luciferase transgene (Luciferase Z-Score = -0.07)." (PMID 28273136, 2017). "In fact, Xenopus and zebrafish embryos injected with DUX4-fl mRNA and mice expressing DUX4-fl via viral infection or transgene expression exhibit phenotypes consistent with FSHD." (PMID 26942723, 2016). "Emerging data support a role for DUX4 in the control of viral infection." (PMID 34943834, 2021). "DUX4 expression blocks the RNA-induced innate immune response to viral infection, which might constitute a mechanism for protecting DUX4-expressing cells from toxicity in some normal developmental contexts compared to the expression of DUX4 in skeletal muscle cells." (PMID 28273136, 2017). "DUX4 is now not only central to FSHD research but roles in early embryogenesis, cancer and viral infection are widening interest in this enigmatic transcription factor." (PMID 40855454, 2025). "In addition, the transient co-expression of ICP0 and ICP4 is sufficient to induce DUX4 expression in the absence of viral infection, whereas an E3-ubiquitin-ligase deficient mutant of ICP0 (ICP0 FXE) was not able to induce expression of DUX4 when coexpressed together with ICP4." (PMID 39814710, 2025). "In addition, the transient co-expression of ICP0 and ICP4 is sufficient to induce DUX4 expression in the absence of viral infection, whereas an E3-ligase deficient mutant of ICP0 (ICP0 FXE) was not able to induce expression of DUX4 when coexpressed together with ICP4." (PMID 38168299, 2023).
B cell acute lymphoblastic leukaemia (5 papers, 2018 to 2025). "A subset of B‐cell acute lymphoblastic leukaemia cases express DUX4 variants or a hybrid DUX4‐IGH fusion gene containing the DUX4 homeodomains." (PMID 34151531, 2021). "Interestingly, the IGH::DUX4 target genes were often associated with the human disease related to precursor B‐cell lymphoblastic leukaemia, reiterating the driving role of this potent oncogenic driver." (PMID 38115701, 2023). "Later, chimeric transcription factors involving DUX4 were found in another cancer, a subset of B cell acute lymphoblastic leukaemia (B-ALL)." (PMID 40855454, 2025). "IGH::DUX4 is frequently observed in 4% B‐cell acute lymphoblastic leukaemia patients." (PMID 38115701, 2023). "In addition, a DUX4-IGH fusion gene is present in a significant proportion of adult B-cell acute lymphoblastic leukaemia patients, where it binds DUX4 response elements and alters the canonical gene expression profile." (PMID 32242220, 2020).
soft tissue sarcoma (4 papers, 2022 to 2024). A malignant neoplasm arising from muscle tissue, adipose tissue, blood vessels, fibrous tissue, or other supportive tissues excluding the bones. "Another study showed that the double homeobox 4 (DUX4) protein is expressed in a wide range of adult solid cancers, including soft-tissue sarcomas, and blocks IFNγ-mediated MHC class I induction in tumor cell lines and immortalized myoblasts." (PMID 38318504, 2023).
breast carcinoma (3 papers, 2017 to 2024). "Results with KM plotter and bc-GenExMiner indicate that DUX4 level is negatively associated with breast cancer prognosis." (PMID 31611907, 2019). "Preliminary investigation of available breast tissue from breast cancer-free women confirmed the demethylation of DUX4 and MTRNR2L2 in a woman showing glyphosate exposure based on urinary test." (PMID 31611907, 2019). "Considering the association of the constituent genes of the GRS formula with luminal breast cancer, such as APOA5 and DUX4, the limitations of its application in non-luminal breast cancer can be taken into account." (PMID 39151519, 2024). "We observed that several genes, specifically RRM2B, HNRNPU, Dux4, SYNCRYP, and WISP-1 are regulated in a similar fashion in tubular epithelial cells as in breast cancer cells whereas remaining genes have not shown similar regulation (data not shown)." (PMID 29254187, 2017).